TFEB (transcription factor EB)
Diseases named in the same sentence as TFEB in open-access papers (continued):
Sharing a sentence is not in itself a finding about the gene and the disease.
breast carcinoma (continued). "To further investigate whether the mechanisms of TFEB regulation by Tam in MCF7 cells are shared by other luminal A breast cancer cell lines, we derived new Tam-resistant cell lines from MDA-MB-415, T47D and ZR-75-1 cells using the same protocol adopted for establishing the MCF7-TamR cells." (PMID 38203629, 2023). "Further investigations will help to clarify whether the alteration of intracellular dynamics of TFEB represents a specific consequence of Tam treatment on luminal A breast cancer cells or rather a prototypical strategy of tumor cells to resist to anticancer treatments." (PMID 38203629, 2023). "And the tumor progression of breast cancer can be inhibited by macrophage-specific TFEB overexpression through enhancing the functional status of immune cells within the tumor microenvironment, as inhibition of TFEB in macrophages obviously leads to the growth of breast cancer." (PMID 34490237, 2021). "Therefore, pharmacological activation of TFEB may be a promising approach to improving the efficacy of existing treatments, including immunotherapies of breast cancer because of favorable modulation of TAM function and of the tumor microenvironment." (PMID 33806255, 2021). "High TFEB expression is correlated with poor prognosis in glioblastoma, non–small-cell lung cancer (NSCLC), and breast cancer." (PMID 40779629, 2025). "To make sure if quercetin promotes ferroptosis in breast cancer cells by controlling TFEB activation of lysosomes, resulting in higher intracellular iron ion levels, in this study, first, we verified that TFEB siRNA could effectively knock down TFEB in MCF-7 cells." (PMID 35898781, 2022). "As expected, lysosomal gene mRNA levels were positively correlated with TFEB and TFE3 levels and negatively correlated with MYC and TET2 levels in breast cancer patients (normal-like tumors, n = 639)." (PMID 35351824, 2022). "TFEB, SIRT1, and Beclin-1 seem to have a potential prognostic significance in patients with chemo-treated breast cancer, likely because of their role in the regulation of autophagy." (PMID 34663249, 2021). "Our preliminary data demonstrate a potential prognostic value of TFEB, SIRT1, and Beclin-1, likely for their role within autophagy regulation in patients affected by breast cancer and treated with anti-blastic therapy." (PMID 34663249, 2021). "This retrospective study analyzes the expression of TFEB, CARM1, SIRT1, and Beclin-1 and the methylation of PITX2 in breast carcinoma." (PMID 34663249, 2021). "• TFEB, SIRT1, and Beclin-1 seem to have a potential prognostic significance in patients with chemo-treated breast cancer." (PMID 34663249, 2021). "Lysosomal biogenesis is mostly triggered by the transcription factors of the MiT/TFE family, especially by the transcription factor EB (TFEB), of which mRNA expression is also augmented in Ctsl−/− breast cancer cells." (PMID 32707827, 2020). "Transcription factor EB (TFEB) overexpression can modulate TAM gene expression and function through multiple pathways, making it a promising approach for improving the efficacy of existing treatments, including immunotherapies for breast cancer." (PMID 38088444, 2024). "Overall, this suggests that expression of TFEB could be critical for regulating TAM protumorigenic functions and could be a therapeutic target for breast cancer." (PMID 32745353, 2020). "Finally, we used two CDK4/6 inhibitors, LY2835219 (Abemaciclib) and PD0332991 (Palbociclib), both of which are used in breast cancer patients, to see whether inhibition of CDK4/6 would reproduce the effects of calcium/ionomycin on TFEB activity." (PMID 38212474, 2024). "We also knocked down TFE3 and TFEB in lung cancer and breast cancer cells where their expression has no negative correlation with patient prognosis and it was found that alteration of the TFE3 or TFEB expression has little effect on tumour maintenance or progression (data not shown)." (PMID 33145941, 2020).
breast carcinoma (continued). "Thus, TFEB is most likely not involved in the regulation of the ErbB2-induced, invasion-promoting lysosomal alterations in breast cancer cells, since ErbB2 activation leads to the activation of the mTOR and MAPK-ERK signaling pathways." (PMID 29396433, 2018). "On the other hand, this correlation is lost in the case of the basal-like subtype, so that in the breast cancer luminal subtypes, we can deduce that both TFEB and CARM1 act in the same pathway, while this may not be true in the case of the basal-like molecular subtype." (PMID 34663249, 2021). "Previous studies have reported that METTL14 forms a negative feedback loop with ALKBH5/TFEB in cardiomyocytes treated with hypoxia/reoxygenation and constitutes a positive one with ALKBH5/HuR in breast cancer." (PMID 36288387, 2022).
lysosomal storage disease (41 papers, 2013 to 2025). A metabolic disorder caused by mutations in proteins critical for lysosomal function, including lysosomal enzymes, lysosomal integral membrane proteins, and proteins involved in the post-translational modification and trafficking of lysosomal proteins. "TFEB overexpression reduces levels of storage material and improves functional outcomes in models of lysosomal storage diseases such as Pompe disease, multiple sulfatase deficiency, and mucopolysaccharidosis." (PMID 40683940, 2025). "As TFEB plays a crucial role in the regulation of various cellular processes, its dysregulation is associated with a host of human diseases, such as lysosomal storage disorders, cancers, metabolic disorders, inflammation and neurodegenerative diseases." (PMID 38365838, 2024). "It follows that TFEB dysregulation contributes to the pathogenesis of lysosomal storage diseases and neurodegenerative diseases associated with aging." (PMID 34268312, 2021). "Previous work demonstrated that overexpression of TFEB promotes reduction of glycosaminoglycans in a mouse model of lysosomal storage disorder due to deficiency of lysosomal enzymes." (PMID 23381957, 2013). "Therefore, TFEB dysregulation has been linked to a variety of human diseases, including lysosomal storage disorders, metabolic disorders, neurodegenerative diseases, and cancers." (PMID 38261662, 2024). "Lysosomal exocytosis may be another mechanism by which TFEB overexpression reduced storage material in Grn–/– mice, as TFEB-mediated clearance of storage material in models of other lysosomal storage disorders has been associated with increased lysosomal exocytosis." (PMID 40683940, 2025). "Defects in multiple features of the lysosomal and autophagic network have been implicated in various neurodegenerative and lysosomal storage disorders, raising the possibility that TFEB could be a promising target to restore lysosomal functions under pathological scenario." (PMID 32457374, 2020). "The protective effects of TFEB in GRN KO cells and Grn–/– mice are consistent with many studies showing beneficial effects of TFEB overexpression in models of lysosomal storage disorders and neurodegenerative diseases." (PMID 40683940, 2025). "This was consistent with the previously reported increase of lysosomal biogenesis and transcription factor EB–driven (TFEB-driven) expression of lysosomal genes in tissues and cells of patients affected with lysosomal storage diseases." (PMID 40540388, 2025). "Targeted regulation of TFEB has been victoriously used as a treatment strategy in several disease models such as ischemic injury, lysosomal storage disorders (LSDs), cancer, metabolic disorders, neurodegenerative diseases, and inflammation." (PMID 38365838, 2024). "Starvation and lysosome storage disorder induced TFEB relocation are the most widely studied, but other stimuli such as lipopolysaccharide (LPS) and pathogens like Staphylococcus aureus have also been shown to promote TFEB nuclear translocation." (PMID 38263327, 2024). "It is thought that activation of the transcription factor TFEB, an inducer of lysosome biogenesis, restores lysosomal-autophagy activity in lysosomal storage disorders." (PMID 38033125, 2023). "Cardiac autophagy dysfunction triggered by lysosomal disorders based on decreased TFEB expression leads to cardiotoxicity of AL-LC and is restored by the administration of rapamycin in neonatal rat ventricular myocytes (NRVMs) and zebrafish." (PMID 35683015, 2022). "As expected, both the activity of TFEB and its nuclear localization together with the autophagic process are affected in several lysosomal disorders." (PMID 35665902, 2022). "Studies have demonstrated beneficial roles of TFEB in neurodegenerative diseases and lysosomal storage diseases primarily owing to its stimulation of the cellular clearance pathways." (PMID 32681035, 2020).
lysosomal storage disease (continued). "The lysosomal calcium channel TRPML1, whose mutations cause the lysosomal storage disorder (LSD) mucolipidosis type IV (MLIV), contributes to upregulate autophagic genes by inducing the nuclear translocation of the transcription factor EB (TFEB)." (PMID 31822666, 2019). "By doing so, TFEB overexpression has been shown to protect against pathological substrate accumulation and cell death in several rodent models of lysosomal storage disorders and neurodegenerative diseases." (PMID 30846695, 2019). "TFEB is probably upregulated as a feedback mechanism to compensate the dysfunctional lysosomes, as was observed in lysosomal storage diseases." (PMID 29643148, 2018). "Recent studies have identified Transcription Factor EB (TFEB) as a potential therapeutic target in lysosomal storage diseases in general, including Pompe disease." (PMID 29118420, 2017). "Certain chemical compounds increase TFEB expression and provide therapeutic efficacy in other lysosomal storage diseases." (PMID 28240313, 2017). "Due to the effect of TFEB activation on lysosomal genes, TFEB has become a therapeutic target for lysosomal storage disorders in general, including the NCLs." (PMID 27083890, 2016). "Stimulation of lysosomal exocytosis via TFEB overexpression has already been shown to promote cellular clearance in lysosomal storage diseases." (PMID 24909901, 2014). "A recently proposed therapeutic approach for lysosomal storage disorders (LSDs) relies upon the ability of transcription factor EB (TFEB) to stimulate autophagy and induce lysosomal exocytosis leading to cellular clearance." (PMID 23606558, 2013). "Hence, pharmacological upregulating lysosome machinery via targeting TFEB represents a promising approach to treat NPC and related lysosomal storage diseases, and provides the possibility of TFEB agonists, that is, SFN as potential NPC therapeutic candidates." (PMID 40184172, 2025). "TFEB’s involvement includes lipid catabolism and it’s a clear potential therapeutic target mediating cellular clearance in a variety of diseases, including rare lysosomal storage diseases and more prevalent ones such as Parkinson’s and Alzheimer’s." (PMID 38978979, 2024). "Previously, it has been shown that TFEB overexpression/activation induces an increased number of autophagosomes and autophagic flux, generation of new lysosomes, and leads to clearance of storage material in lysosomal storage disorders (LSDs)." (PMID 38978979, 2024). "TFEB is a member of the MiTF/TFE family of basic helix-loop-helix leucine zipper transcription factors, linked to a range of conditions including neurodegenerative diseases, metabolic disorders, obesity, tumors, and lysosomal storage diseases." (PMID 38664707, 2024). "A recent study reported that TFEB regulates lysosomal exocytosis, and induction of lysosomal exocytosis by TFEB overexpression has been shown to rescue pathologic storage and restore normal cellular morphology in lysosomal storage disease (LSD)." (PMID 36649084, 2023). "Since TFEB overexpression is able to restore lysosomal morphology and function in various cellular and animal models of lysosomal storage diseases, we wondered whether its expression may also rescue the endolysosomal iron overload-associated cytotoxicity." (PMID 36522443, 2022). "The nodal function of TFEB in ALP promoted the development of TFEB-based gene therapy predominantly by its overexpression to treat lysosomal storage disorders, which was successfully tested in cell and mouse models of Pompe’s disease, Gaucher’s disease, and amyotrophic lateral sclerosis." (PMID 35682624, 2022). "YAP promotes cardiomyopathy through the activation of TFEB in lysosomal storage disorder." (PMID 35402535, 2022). "By promoting lysosomal secretion, TFEB overexpression in mouse embryonic fibroblasts increased number of autophagosomes and autophagic flux, generation of new lysosomes, and led to clearance of storage material in several lysosomal storage disorders." (PMID 33685494, 2021).
lysosomal storage disease (continued). "Interestingly, a recent study showed that HPβCD treatment enhances autophagy through the activation of TFEB in the model of another lysosomal storage disorder, neuronal ceroid lipofuscinosis." (PMID 32457374, 2020). "Another group of diseases in which TFEB and the other transcription factors of the MiTF/TFE family seem to play an important role are lysosomal storage disorders (LSDs)." (PMID 35665902, 2022). "Overexpression of TFEB and TFE3 has been shown to promote the elimination of storage material and ameliorate the pathological findings of various lysosomal storage diseases." (PMID 28301521, 2017). "In murine models of lysosomal storage disease, activation of TFEB was able to increase autophagic flux in muscle, but in our studies, TFEB activation did not restore lysosomal homeostasis or autophagy in the presence of defective ALR." (PMID 33119550, 2021). "Activation of lysosomal exocytosis by the transcription factor EB (TFEB) promoted cellular clearance in cultured cells from various lysosomal storage disease animal and human models, but Fabry disease was not tested." (PMID 27081853, 2016). "Studies performed in several lysosomal storage disorder (LSD) and neurodegenerative disease models suggest that enhancing both lysosomal and autophagic functions by overexpression/activation of Transcription Factor EB (TFEB) could be a more beneficial therapeutic approach 21,23–25." (PMID 40395298, 2023). "However, if the overexpression of TFEB over a longer period could lead to cardiac side effects, especially in mice that do not have a lysosomal storage disease, has not been investigated." (PMID 35682624, 2022).
Parkinson disease (39 papers, 2014 to 2026). A progressive degenerative disorder of the central nervous system characterized by loss of dopamine producing neurons in the substantia nigra and the presence of Lewy bodies in the substantia nigra and locus coeruleus. "The co-existence of mTORC1 hyperactivation and lysosomal dysfunction has also been found in some genetic models of Parkinson's disease, which was linked to impaired TFEB activity." (PMID 31519738, 2019). "Furthermore, loss of function of GBA1, mutations of which are the most common genetic cause of sporadic Parkinson's disease, increases TFEB turnover, further impairing transcriptional induction of macro‐autophagy and exacerbating (alpha)‐synucleinopathy." (PMID 37728021, 2023). "TFEB transcript levels rose significantly after ambroxol treatment in control (2.25-fold increase, Mann-Whitney U-test P = 0.02), Gaucher disease (2.5-fold increase, P = 0.01) and Parkinson’s disease with GBA mutation fibroblasts (1.75-fold increase, P = 0.03)." (PMID 24574503, 2014). "Our findings identify KHS-101 as a potent TFEB activator and highlight the therapeutic potential of modulating the autophagy-lysosomal pathway for treating Parkinson’s disease and related disorders." (PMID 41596551, 2026). "For Parkinson’s disease, the possible mechanism of curcumin is to enhance autophagy by promoting TFEB nuclear transport." (PMID 40918536, 2025). "In some neurodegenerative disorders, including polyglutamine disease and Parkinson’s disease, pathogenesis is exacerbated by decreasing TFEB function, which impairs autophagy." (PMID 37611054, 2023). "In mice models of Parkinson’s and AD, overexpression of TFEB resulted in enhanced degradation of bulk autophagy substrates and help in the clearance of damaged mitochondria and lipid droplets." (PMID 34970114, 2021). "Studies have shown that TFEB can improve neurodegenerative diseases, such as Huntington’s disease and Parkinson’s disease." (PMID 33935747, 2021). "TFEB (transcription factor EB), which is a master regulator of autophagy and lysosome biogenesis, is considered to be a new therapeutic target for Parkinson’s disease (PD)." (PMID 32098449, 2020). "An increase in the phosphorylated form of TFEB and dysregulation of autophagy has been correlated with the progression of neurodegenerative diseases, including Parkinson's." (PMID 33224433, 2020). "The therapeutic potential of TFEB in Parkinson’s disease was further highlighted by a recent study that showed restored TFEB and improved neurological function upon rapamycin treatment in Q311X mutant parkin mice independently of the parkin E3 ligase." (PMID 32373609, 2020). "Inhibition of PARP1 promotes TFEB‐mediated autophagy and then increases the degradation of α‐synuclein, providing a potential therapeutic strategy of Parkinson’s disease." (PMID 32475059, 2020). "This is also consistent with recent reports that TFEB overexpression effectively blocks the development α-syn-induced pathology while protecting nigral DA neurons in rats with Parkinson's disease." (PMID 27195074, 2016). "Ambroxol hydrochloride increases glucosylceramidase activity in control, Gaucher disease and Parkinson’s disease with GBA mutation cell lines, by activating components of the CLEAR network through TFEB combined with chaperone activity." (PMID 24574503, 2014). "Given that TFEB activation mitigates toxic protein accumulation in neurodegenerative diseases such as Parkinson’s disease (PD), we investigated whether KHS-101 reduces levels of A53T mutant α-synuclein, a key pathological hallmark of PD." (PMID 41596551, 2026). "While this effect was suggested to occur through cholesterol extraction, a subsequent study suggested an alternative mechanism of action by demonstrating that in a cellular Parkinson model 1 mM HPβCD activated TFEB (transcription factor EB), a major regulator of lysosomal functions." (PMID 36559052, 2022).